MIR655 (microRNA 655)
Synonyms: hsa-mir-655; MIRN655; mir-655
Gene: MicroRNA gene on chromosome 14 (101,049,550 to 101,049,646, forward strand). Ensembl gene ENSG00000207646.
Gene Ontology:
Biological process: miRNA-mediated post-transcriptional gene silencing
Cellular component: RISC complex
Diseases named in the same sentence as MIR655 in open-access papers:
MIR655 is named in the same sentence as 2 diseases in open-access papers, as found by Europe PMC text mining. Sharing a sentence is not in itself a finding about the gene and the disease.
MIR655 shares sentences with these, for which no sentence is quoted: breast carcinoma (1 paper); Tumour (1).